NIPSNAP2 (nipsnap homolog 2)
Description:
Protein involved in mitophagy by facilitating recruitment of the autophagy machinery required for clearance of damaged mitochondria. Accumulates on the mitochondria surface in response to mitochondrial depolarization and acts as a 'eat me' signal by recruiting proteins involved in selective autophagy, such as autophagy receptors (CALCOCO2/NDP52, NBR1, SQSTM1/p62, TAX1BP1 and WDFY3/ALFY) and ATG8 family proteins (MAP1LC3A, MAP1LC3B, MAP1LC3C, GABARAP, GABARAPL1 and GABARAPL2).
Synonyms: GBAS
Tractability: PROTAC: ubiquitination databases record sites on it.
Gene: Protein-coding gene on chromosome 7 (55,951,793 to 56,000,181, forward strand). Ensembl gene ENSG00000146729.
Subcellular location: Mitochondrion matrix
Subcellular location (Human Protein Atlas): Mitochondria
Pathways (Reactome):
Signal Transduction: RHOH GTPase cycle; RHOJ GTPase cycle
Gene Ontology:
Molecular function: protein binding; protein-macromolecule adaptor activity
Biological process: mitochondrion organization; mitophagy; positive regulation of high voltage-gated calcium channel activity
Cellular component: mitochondrial matrix; mitochondrial outer membrane; mitochondrion
Genetic constraint (gnomAD): Loss-of-function variants: 26 observed, 30.17 expected, observed/expected ratio (o/e) 0.86, 90% interval 0.63 to 1.2. The upper end of that interval is the gene's LOEUF score, 1.2, which puts it in group 5 of 6, group 1 being the genes least tolerant of losing a copy. Missense variants: 192 observed, 247.55 expected, observed/expected ratio (o/e) 0.78, 90% interval 0.69 to 0.87. Synonymous variants: 98 observed, 87.42 expected, observed/expected ratio (o/e) 1.12, 90% interval 0.95 to 1.33.
Homologues: Orthologues: chimpanzee NIPSNAP2 (99% identical), macaque NIPSNAP2 (97% identical), dog NIPSNAP2 (94% identical), guinea pig NIPSNAP2 (91% identical), rat Nipsnap2 (91% identical), mouse Nipsnap2 (90% identical), rabbit NIPSNAP2 (87% identical), tropical clawed frog nipsnap2 (80% identical), zebrafish nipsnap2 (57% identical), Drosophila melanogaster Nipsnap (43% identical), Caenorhabditis elegans K02D10.1 (38% identical). Paralogues in human: NIPSNAP1 (69% identical), NIPSNAP3B (22% identical), NIPSNAP3A (21% identical).
Diseases named in the same sentence as NIPSNAP2 in open-access papers:
NIPSNAP2 is named in the same sentence as 5 diseases in open-access papers, as found by Europe PMC text mining. Sharing a sentence is not in itself a finding about the gene and the disease.
NIPSNAP2 shares sentences with these, for which no sentence is quoted: glioblastoma (3 papers); tumor (2); cancer (1); cataract (1); leukemia (1).